ICAM1 (intercellular adhesion molecule 1)
Diseases named in the same sentence as ICAM1 in open-access papers (continued):
Sharing a sentence is not in itself a finding about the gene and the disease.
diabetes (continued). "Particles have been shown to increase sICAM-1 (soluble intercellular adhesion molecule-1) and sVCAM-1 (soluble vascular adhesion molecule 1) in diabetics, a finding confirmed in a controlled human exposure chamber study." (PMID 19590680, 2009). "Previous reports have shown that IFN-α can induce the expression of CD86 and ICAM-1 in murine Mac-1 monocytes/macrophages in a model of diabetes induction in vivo." (PMID 18588665, 2008). "ICAM-1 mediates the adhesion of neutrophils and monocytes to the vascular endothelium, and increased ICAM-1 levels have been found in the blood and in the retinal vasculature of patients with diabetes." (PMID 17653050, 2007). "This leukostasis is known to be increased inretinal blood vessels in diabetes, and this process is mediated via ICAM-1." (PMID 18274606, 2007). "ICAM-1 upregulation has been observed in the retinal vessels of patients with diabetes." (PMID 40297222, 2025). "Additionally, other endothelial cell adhesion molecules, including E-selectin, vascular cell adhesion molecule-1 (VCAM-1), and intercellular adhesion molecule-1 (ICAM-1), were upregulated in diabetes, and their overexpression was positively correlated with OS." (PMID 39064844, 2024). "Furthermore, knocking down ARG1 reduced the high expression levels of vascular endothelial adhesion molecules (Icam1, Et-1, and Vcam1) induced by diabetes." (PMID 39235443, 2024). "In the diabetes group, ICAM-1 gene expression was upregulated than the control group (p < 0.05)." (PMID 39742025, 2024). "Of note, the overexpression of intercellular adhesion molecule-1 (ICAM-1), which is a transmembrane protein involved in the inflammatory response, has been observed in both patients with AC and diabetes, possibly explaining the common association between the two conditions." (PMID 37998547, 2023). "We therefore postulated that STING’s contribution to retinal leukostasis in diabetes may be mediated by enhanced expression of ICAM-1 by IFN-β–induced senescent endothelial cells." (PMID 37345657, 2023). "Relevant studies have pointed out patients with diabetes have elevated ICAM-1." (PMID 38084239, 2023). "Diabetes-induced retinal superoxide, expression of proinflammatory genes Inos and Icam1, leucostasis and leucocyte-mediated cytotoxicity against retinal endothelial cells were inhibited in diabetic Ccr2-deficient mice and in chimeric mice lacking Ccr2 only from myeloid cells." (PMID 36698021, 2023). "In addition, diabetes-induced increases in retinal inflammatory proteins iNOS, IL-1α, and IL-10, and ICAM-1 were also inhibited in STING-KO and STINGGT diabetic mice." (PMID 37345657, 2023). "To explore the potential predictive value of the ICAM-1 gene variants, we attempted to establish a nomogram to compare ICAM-1 rs5491 genotypes, age, smoking, diabetes, hemoglobin, LDL-C, left ventricular ejection fraction, and NT-proBNP to predict the risk of ICM." (PMID 36440000, 2022). "Vascular risk factors including hyperglycemia, advanced glycation end products (AGEs), oxidized lipids found in diabetes and obesity can elevate the expressions of VCAM-1 and ICAM-1 and cause inflammation, and inflammation aggravates the progression of cardiovascular disease." (PMID 36558380, 2022). "In systemic lupus erythematosus (SLE), diabetes, and rheumatoid arthritis (RA), this is regulated by inhibition of galectin-mediated immunosuppressive prevention of ICAM-1/LFA-1 interaction, aberrant expression of ICAM-1 N-glycans due to high glucose, and activity of glycosyltransferases." (PMID 35833138, 2022). "Additionally, variants in ICAM1 and serum ICAM-1 levels are also associated with the development of diabetes and diabetic nephropathy." (PMID 36277770, 2022). "Hence, the anti-inflammatory effect of C66 in diabetes-associated renal impairment appears to be the result partially of the suppressed expression of VCAM-1, ICAM-1, and MCP-1 in the renal epithelium." (PMID 36316651, 2022).
diabetes (continued). "Collectively, these results strongly suggest that ICAM-1 mediates renal damage in diabetes." (PMID 36364178, 2022). "Moreover, pharmacological blockade of p300/CBP significantly reduced the diabetes-associated inflammatory response in the kidney, as demonstrated by the knock-down effects on MCP-1, TNFα, NOS2, ICAM-1, VCAM-1, and E-selectin transcript levels." (PMID 34572988, 2021). "Retinal abnormalities that have been implicated in the development of the retinopathy (superoxide generation and expression of inflammatory proteins, iNOS and ICAM-1) were evaluated at 2 months of diabetes, and retinal capillary degeneration was evaluated at 8 months of diabetes." (PMID 32941450, 2020). "The aim of this study was to evaluate the relationship between adipocytokines (leptin, ghrelin, and chemerin), inflammation (sVCAM1—soluble vascular adhesion molecule 1, sICAM1—soluble intercellular adhesion molecule 1), and insulin resistance in the presence of obesity and diabetes mellitus." (PMID 32858998, 2020). "As a main proinflammatory mediator, IL-6 has a direct toxic effect on islet cells and can upregulate the expression level of ICAM-1, mediated by IL-1-induced by reactive oxygen species, leading to further damage to the epithelium, as well as accelerating the onset of diabetes." (PMID 32082400, 2020). "After induction of the diabetes, both sexes responded similarly with respect to the oxidative stress, expression of iNOS, and degeneration of retinal capillaries, but differed in the limited population evaluated with respect to expression of ICAM-1." (PMID 32941450, 2020). "Since increased expression of proinflammatory proteins also has been implicated in the pathogenesis of the retinopathy in studies of male mice, we compared the effects of diabetes on the expression of inflammatory proteins iNOS and ICAM-1 in diabetic male and female mice." (PMID 32941450, 2020). "In diabetes, the blood levels of ICAM-1 are increased, which could be a predictor of macrovascular complications such as myocardial infarct or stroke." (PMID 31934591, 2019). "Interestingly, selective inhibition of NF-κB activation with dehydroxymethylepoxyquinomicin inhibited diabetes-induced retinal leukostasis and retinal expressions of ICAM-1 and VEGF in vivo." (PMID 31337130, 2019). "It has been demonstrated, that it effectively inhibits diabetes induced increase in superoxide production, leukostasis and ICAM-1 expression in STZ induced rats, which resulted in a significant reduction in ganglion cell death and improvement of the photopic b wave ERG amplitude." (PMID 29565290, 2018). "Among the cytokines, ICAM-1 is closely related with diabetes characteristics." (PMID 29784048, 2018). "Non-targeted discovery approaches assessing the gene expression profile of Müller cells after 6 months of STZ induced diabetes, revealed that among 78 altered genes, one third are associated with inflammation, including complement factors, VEGF, ICAM-1 and IL-1β." (PMID 29565290, 2018). "However, significant reduction of frequencies of the dominant model of ICAM1 rs5498 was only detected in the Caucasian subgroup (OR = 0.80; 95% CI = [0.65, 0.99], p = 0.04) and type 1 diabetes mellitus subgroup (OR = 0.80; 95% CI = [0.65, 0.99], p = 0.04)." (PMID 30587209, 2018). "The assumption that metformin could directly modulate molecular events in DR progression, rather than through controlling blood glucose, was supported by clinical evidences that metformin significantly reduced plasma ICAM-1 in diabetes patients." (PMID 29854819, 2018). "ICAM-1 was upregulated in the retina and vitreous of DR patients and diabetes rodent models." (PMID 29854819, 2018). "A high level of serum ICAM-1 has been reported in coronary arthritis and diabetes patients." (PMID 29696063, 2018).
diabetes (continued). "Our findings are inconsistent with other studies because of the clinical status of their participants (subjects with coronary arthritis and diabetes) and their exercise training protocol (supervised exercise training program) that resulted in a reduction in serum ICAM-1." (PMID 29696063, 2018). "In addition, retinopathy has been revealed to be an inflammatory factor and leukostasis and increased levels of ICAM1, a member of the 80–114 kD immunoglobulin gene superfamily, which has been observed in retina in diabetes and hyperglycaemia." (PMID 28738845, 2017). "In vivo inhibition of NFAT with A-285222 decreased the expression of OPN and ICAM-1 mRNA in retinal vessels, prevented a diabetes driven downregulation of anti-inflammatory IL-10 in retina, and abrogated the increased vascular permeability observed in diabetic mice." (PMID 25918731, 2015). "Real-time PCR (RT-PCR) revealed that STZ-induced diabetes was associated with significantly up-regulated MCP-1 (Mcp1), CSF-1 (Csf1), ICAM-1 (Icam1), and VCAM-1 (Vcam1) expression in Nrf2+/+ and Nrf2−/− mice, and these changes in expression were reversed by digitoflavone in Nrf2+/+ mice only." (PMID 26205695, 2015). "ICAM-1, an important adhesion molecule related to vascular inflammation, promotes inflammatory cells including mononuclear macrophage infiltration into glomeruli and renal interstitium and accelerates glomerular sclerosis in diabetes." (PMID 25880429, 2015). "Moreover, in TLR2-/- and TLR4-/- mice induced with diabetes, there was an amelioration of glomeruli ICAM-1 expression versus wildtype diabetic mice." (PMID 25303153, 2014). "Besides Akt/NF-κB pathway changes, PAI-1 and ICAM-1 were also increased in diabetes kidney in the protein levels." (PMID 24672545, 2014). "However, with the induction of diabetes, there was a marked upregulation in ICAM-1 expression in the glomeruli." (PMID 25303153, 2014). "Furthermore, the increased expression of PAI-1 and intercellular adhesion molecule-1 in diabetic renal cortex were also reduced by RSV administration." (PMID 24672545, 2014). "Therefore, the present study aims to investigate the mechanism of curcumin on diabetes-induced vascular complications related to these molecular biomarkers including Txnip, ICAM-1, and NOX2 expressions using STZ-induced diabetic rat model." (PMID 25054130, 2014). "Various studies have demonstrated that inhibition of pro-inflammatory cytokines (such as IL-1β, TNF-α, and VEGF), chemokines (such as MCP-1), or adhesion molecules (such as ICAM-1) can reduce diabetes-induced leukostasis, degeneration of retinal capillaries, or BRB breakdown." (PMID 23662142, 2013). "ICAM-1 is a known important downstream inflammatory factor whose overexpression promotes inflammatory cells, including mononuclear macrophage infiltration into glomeruli and renal interstitium, as well as accelerates glomerular sclerosis in diabetes." (PMID 24499158, 2013). "In diabetes, activated nuclear factor-κB (NF-κB) translocates into the nucleus and triggers the expression of its target genes, including intercellular adhesion molecule-1 (ICAM-1) and transforming growth factor-beta 1 (TGF-β1)." (PMID 23718910, 2013). "Effect of diabetes on ICAM-1 and VCAM-1 was significantly blocked by baicalein." (PMID 23437353, 2013). "In vivo antibody therapy against ICAM1 or CD18 has been reported to inhibit diabetes-induced retinal leukostasis and endothelial injury in mice, suggesting that integrin/CAMs might make a good target for therapy." (PMID 24205223, 2013). "Mean values of ICAM-1 within this control population were significantly lower than in a composite impaired glucose tolerant and diabetes group among all subjects (P < 0.001) and when South Asian (P = 0.015) and white European (P = 0.015) subjects were analysed separately." (PMID 23304116, 2012).
diabetes (continued). "Although the picture of ICAM1 involvement and interaction is complex, experiments have indicated that inhibition of the ICAM1 gene expression may improve the progress of diabetes and DN." (PMID 23346076, 2012). "First, the ICAM1 gene is located in a linkage region with diabetes and DN." (PMID 23346076, 2012). "The ICAM1 gene is located on chromosome 19p13 within the linkage region of diabetes." (PMID 23346076, 2012). "Collectively, it seems that diet-induced VCAM-1 expression may be driven by serum cholesterol, whereas diabetes-induced ICAM-1 expression may be driven by triglycerides in ApoE−/− mice, by a mechanism yet to be described." (PMID 20856927, 2010). "Interestingly, we found that genetic inhibition of STING attenuates diabetes-induced phosphorylation of TBK1, IKK, IκB, and NF-κB, which is associated with reduced iNOS and ICAM-1 expression along with decreased superoxide production and leukostasis in STING-perturbed diabetic mice." (PMID 37345657, 2023). "Diabetes induced a significant increase in the number of ICAM‐1+ blood vessels/cm2 (controls: 12 ± 1 in the ventricles and 11 ± 2 in the atria; DM group: 23 ± 4 in the ventricles (p = .007) and 22 ± 2 in the atria (p = .02)." (PMID 35488737, 2022). "Under a low dosage (300 mg/kg), it could decrease diabetic vascular inflammation by reducing leukocyte–endothelium interaction and inhibiting the expression of intercellular adhesion molecule 1 (ICAM-1) and pro-oxidant NADPH oxidase (NOX2) in a diabetic rat model." (PMID 36430891, 2022). "However, the presence of higher levels of sICAM in those with DR can be explained by the fact that diabetes increases the level of ICAM-1 on the luminal surface of endothelial cells in the retina when compared with other tissues as described in a recently published experimental study." (PMID 36167607, 2022). "Diabetes induced a significant increase in the number of ICAM‐1+ blood vessels/cm2 (controls: 52.6 ± 30.7; DM group: 86.6 ± 21.8, p = .02) and the percentage of ICAM‐1+ glomeruli (controls: 33.7 ± 25.6; DM group: 64.6 ± 16.4, p = .02)." (PMID 35488737, 2022). "Moreover, in vivo inhibition of NFAT decreased the retinal vascular expression of OPN and ICAM-1, prevented diabetes-induced retinal downregulation of the anti-inflammatory cytokine IL-10, and eliminated the phenomenon of increased vascular permeability in diabetic mice." (PMID 33791348, 2021). "Diabetic retinopathy (DR), the most common complication of diabetes mellitus, is associated with oxidative stress, nuclear factor-κB (NFκB) activation, and excess production of vascular endothelial growth factor (VEGF) and intracellular adhesion molecule-1 (ICAM-1)." (PMID 34860856, 2021). "The importance of platelet-derived CAPN1 in the vascular complications of diabetes was demonstrated by the fact that diabetes induction in CAPN1ΔPF4 mice failed to increase circulating levels of the EPCR or to alter the surface expression of PAR-1 or ICAM-1 on endothelial cells." (PMID 33258989, 2020). "Besides, CW could significantly decrease the elevation of IL-6 and ICAM-1 levels induced by diabetes mellitus in the rat retina (P < 0.05 and 0.05 compared with the DM group)." (PMID 32082400, 2020). "Blocking ICAM-1 signaling abrogated the infiltration of macrophages in kidneys from diabetic rats and decreased glomerular hypertrophy and interstitial fibrosis in ICAM-1-deficient mice indicating a potential role of ICAM-1 in the progression of renal injury during diabetes." (PMID 22518298, 2012). "Inhibition of ICAM1 gene activity may benefit in treatment of diabetes and DN." (PMID 23346076, 2012). "Since ICAM-1 expression on endothelial cells plays a critical role in inflammation through the adhesion of white blood cells to the vessel wall (leukostasis), we measured the effect of diabetes and the therapy on the expression of ICAM-1 in retinas and on leukostasis." (PMID 22171162, 2011).
diabetes (continued). "EMPA-treated STEMI patients exhibit lower thrombomodulin and ICAM-1 levels, which indicate endothelial protection after STEMI but also reduced microvascular complications due to diabetes." (PMID 39958474, 2025). "MSCs treatment attenuated the expression of ICAM1 and VCAM1 in the aortic endothelium, which was enhanced by diabetes;however, the anti-inflammatory phenotype of MSCs was abolished when STC1 was knocked down." (PMID 41249792, 2025). "The intravitreal administration of ADAMTS13 attenuates diabetes-induced BRB breakdown, the downregulation of VE-cadherin and β-catenin, and the upregulation of VWF, CD41, phospho-ERK1/2, HMGB1, VCAM-1, and ICAM-1." (PMID 39851513, 2025). "Increased TNF‐α and ICAM‐1, predicted the incidence of DPN over 5 years in Chinese diabetes patients." (PMID 37795833, 2024). "In diabetes, both treatments reduced systolic blood pressure, gliosis, vascular leakage, and microglial/macrophage density, but only finerenone lowered VEGF, ICAM-1, and IL-1ß." (PMID 36768656, 2023). "The results of this study show that diabetes induction increases IR, urine volume, water consumption, GFR, urine glucose, urine albumin, urine urea, and kidney NOX4 and ICAM1 gene expressions in both female and male mice, as well as in the offspring." (PMID 36755074, 2023). "ICAM-1 is increased in retinas from STZ-induced diabetic mice, mediating endothelium damage and leakage, ultimately contributing to BRB dysfunction in diabetes." (PMID 36869375, 2023). "Previous studies have revealed that HMGB1 inhibitor GA treatment protects against kidney lesions induced by diabetes, which is related to the reduced expression of TNF-α, 1L-6, IL-1β, MCP-1, and ICAM-1 in the kidney." (PMID 35578754, 2022). "Curcumin significantly inhibits the activation of CaMKII/NF-κB signaling induced by diabetes or elevated glucose levels, and it subsequently decreases the expression of VEGF, iNOS and ICAM-1." (PMID 35408920, 2022). "The leukostasis is known to be increased in retinal blood vessels in diabetes, and this process is mediated via ICAM-1, while the retinal ICAM-1 levels were significantly increase when compared with the nondiabetic control group after 1 week of diabetes." (PMID 35126785, 2022). "Diabetes models have shown an influx of macrophages in response to increases in MCP-1 and ICAM-1, and inhibiting this influx can reduce proteinuria." (PMID 35418167, 2022). "The Nrf2 activator dh404 prevented an increase in diabetes-induced inflammatory mediators, including TNF-α, IL-6, ICAM-1, and MCP-1, in Müller cells." (PMID 34938383, 2021). "The expression levels of ICAM-1 and IL-1β were lower in the FGF-1 treatment group than in the diabetes group (p < 0.05)." (PMID 34281287, 2021). "Diet-induced obesity and diabetes alike enhance the expression of endothelial transmembrane proteins in the heart, such as VCAM-1 and ICAM-1, which facilitate leucocyte adhesion to the vascular wall and endothelial transmigration." (PMID 34671656, 2021). "After inhibiting NFAT for 4 weeks, the expression levels of OPN and ICAM-1 in the retinal vascular basement were decreased, and inhibition of NFAT in vivo eliminated the increase in vascular permeability induced by diabetes." (PMID 33791348, 2021). "Duration of diabetes, body mass index, serum HbA1c, vascular endothelial growth factor (VEGF), APN, pentraxin 3 (PTX3), platelet derived growth factor (PDGF), intercellular adhesion molecule-1 (ICAM-1), and APN were measured and analyzed." (PMID 34780524, 2021). "On the contrary, PPARα overexpression in rats with streptozotocin(STZ)-induced diabetes reduces vascular leakage and retinal inflammation by decreasing adherent leukocytes and expression levels of VEGF, TNF-α, and ICAM-1." (PMID 33291567, 2020). "Other than that, chronic inflammation in patients with diabetes mellitus demonstrated increased circulating vascular cell adhesion molecule-1 (VCAM-1) and intracellular adhesion molecule-1 (ICAM-1)." (PMID 32456230, 2020).